ENGASE (endo-beta-N-acetylglucosaminidase)
Description:
Endoglycosidase that releases N-glycans from glycoproteins by cleaving the beta-1,4-glycosidic bond in the N,N'-diacetylchitobiose core. Involved in the processing of free oligosaccharides in the cytosol.
Synonyms: FLJ21865
Tractability: Small molecule: a high-quality ligand is known; it belongs to a druggable protein family. PROTAC: ubiquitination databases record sites on it; its protein half-life has been measured; a small molecule that binds it is known.
Target class: Enzyme; Hydrolase
Gene: Protein-coding gene on chromosome 17 (79,074,824 to 79,088,599, forward strand). Ensembl gene ENSG00000167280.
Subcellular location: Cytoplasm, cytosol
Subcellular location (Human Protein Atlas): Cytosol; Centrosome
Pathways (Reactome):
Metabolism of proteins: N-glycan trimming in the ER and Calnexin/Calreticulin cycle
Gene Ontology:
Molecular function: mannosyl-glycoprotein endo-beta-N-acetylglucosaminidase activity
Biological process: protein folding
Cellular component: cytosol; cytoplasm
Genetic constraint (gnomAD): Loss-of-function variants: 67 observed, 80.69 expected, observed/expected ratio (o/e) 0.83, 90% interval 0.68 to 1.02. The upper end of that interval is the gene's LOEUF score, 1.02, which puts it in group 4 of 6, group 1 being the genes least tolerant of losing a copy. Missense variants: 911 observed, 964.81 expected, observed/expected ratio (o/e) 0.94, 90% interval 0.89 to 1. Synonymous variants: 389 observed, 394.36 expected, observed/expected ratio (o/e) 0.99, 90% interval 0.91 to 1.07.
Homologues: Orthologues: chimpanzee ENGASE (99% identical), macaque ENGASE (95% identical), guinea pig ENGASE (79% identical), mouse Engase (78% identical), pig ENGASE (78% identical), rat Engase (76% identical), dog ENGASE (75% identical), tropical clawed frog engase (48% identical), zebrafish engase (47% identical), Drosophila melanogaster ENGase (27% identical), Caenorhabditis elegans eng-1 (22% identical).
Diseases named in the same sentence as ENGASE in open-access papers:
ENGASE is named in the same sentence as 4 diseases in open-access papers, as found by Europe PMC text mining. Sharing a sentence is not in itself a finding about the gene and the disease. The quoted sentences say what the papers report.
psychosis (1 paper, 2021). "Our findings support the use of MMN as an endophenotype for psychosis and implicate FAM89A and ENGASE as key components of the physiology of prediction error minimization." (PMID 33730571, 2021).
Stroke (1 paper, 2026). Sudden impairment of blood flow to a part of the brain due to occlusion or rupture of an artery to the brain. "We identified 7 potential risk genes (MMP12, F11, SH3BGRL3, ENGASE, SCARA5, SWAP70 and SPATA20) of stroke with altered protein abundances in the plasma." (PMID 41488603, 2026). "The PWAS identified 7 genes (MMP12, F11, ENGASE, SH3BGRL3, SPATA20, SWAP70, SCARA5) whose cis-regulated plasma protein levels were associated with stroke and its subtypes at a FDR of P < 0.05." (PMID 41488603, 2026). "We found that the protein abundance of seven genes (MMP12, F11, SH3BGRL3, ENGASE, SCARA5, SWAP70 and SPATA20) in the plasma was associated with stroke and its subtypes, and six genes (MMP12, F11, SH3BGRL3, SCARA5, SWAP70 and SPATA20) causally related with stroke and its subtypes." (PMID 41488603, 2026).
infection (1 paper, 2024). The state of being infected such as from the introduction of a foreign agent such as serum, vaccine, antigenic substance or organism. "It was proposed that this ENGase can inactivate host glycoproteins to provide an advantage to the bacteria during infection." (PMID 38879612, 2024).
ENGASE also shares sentences with these, for which no sentence is quoted: C. perfringens infection (1 paper).